RAD51C (RAD51 paralog C)
Diseases named in the same sentence as RAD51C in open-access papers (continued):
Sharing a sentence is not in itself a finding about the gene and the disease.
lung carcinoma (5 papers, 2016 to 2024). "We demonstrated variable prevalence of these two methylation events across cancer types, ranging from rare (e.g. BRCA1 methylation in lung cancer) to highly prevalent (e.g. RAD51C methylation in STAD and BRCA1 methylation in individuals of African ancestry with BC)." (PMID 39055334, 2024).
non-small cell lung carcinoma (5 papers, 2012 to 2023). A group of at least three distinct histological types of lung cancer, including non-small cell squamous cell carcinoma, adenocarcinoma, and large cell carcinoma. "Overexpression of RAD51C in non-small cell lung cancer cells increased cisplatin resistance and radiotherapy, and high expression of RAD51C in non-small cell lung cancer tissues was significantly associated with poor prognoses of the patients." (PMID 36319719, 2022). "Possible candidates are CLTC, involved in gene fusions in B-cell lymphomas and non-small cell lung carcinomas, and RAD51C involved in DNA repair and homologous recombination." (PMID 22719901, 2012). "Herein, we took advantage of TCGA data, screening candidate DNA-repair genes (RAD51B, RAD51C, RAD51D, XRCC2, and XRCC3) with covariance and correlation matrices in mRNA level from complete 1124 complete cases of non-small cell lung cancer clinical data." (PMID 29207658, 2017).
colon cancer (4 papers, 2016 to 2024). "RAD51C, RFC4, and SIRT5 exhibited a low differential expression in Caco-2 cells treated with LEVs but a high differential expression in TCGA colon cancer tissue samples." (PMID 39110260, 2024). "Next, we confirmed the expression of RAD51C, RFC4, SIRT1, SIRT5, and SMAD3 genes in different colon cancer cell lines." (PMID 39110260, 2024).
colorectal cancer (4 papers, 2012 to 2024). A primary or metastatic malignant neoplasm that affects the colon or rectum. "Here we have genotyped the RAD51C mutations c.837 + 1G > A and c.93delG in 1083 prostate and 802 colorectal cancer patients to assess the risk for these cancer types." (PMID 23176254, 2012). "In conclusion, we did not detect the Finnish founder mutations in the RAD51C gene among 1083 prostate and 802 colorectal cancer patients suggesting that the RAD51C mutations do not predispose to prostate or colorectal cancer." (PMID 23176254, 2012). "No RAD51C mutations c.837 + 1G > A or c.93delG were detected among the prostate or colorectal cancer patients." (PMID 23176254, 2012). "The results suggest that the RAD51C mutations do not predispose to prostate or colorectal cancer." (PMID 23176254, 2012).
gastric cancer (4 papers, 2019 to 2024). A primary or metastatic malignant neoplasm involving the stomach. "However, we did observe a subset of RAD51C methylated stomach cancer cases with LOH and evidence of HRD-associated scarring (albeit not at the HRD score threshold of 42)." (PMID 39055334, 2024). "On the other hand, in EBV-driven CIMP+ stomach cancer, RAD51C methylation is likely a consequence of the global CpG island methylation." (PMID 39055334, 2024). "The role of multiple PARP inhibitors has also been evaluated in gastric cancer (GC) conditions as mutated homologous DNA recombination genes such as BRC1/2, PALB2, ATM, RAD51C, and ARID1A carry somatic HRD." (PMID 35873570, 2022). "Our group, as a member of The Latin American Gastric Cancer Genetics Collaborative Group, recently described the role of germline mutations in homologous recombination pathway related genes such as PALB2, BRCA1, and RAD51C in patients with GC." (PMID 31600923, 2019). "Interestingly, RAD51C promoter was almost ubiquitously methylated in CIMP+ stomach cancer cases, but mostly at low tumour methylation level (likely heterozygous), suggesting that homozygous RAD51C methylation may offer a growth disadvantage in the stomach cancer development." (PMID 39055334, 2024). "Indeed, this patient presented the typical clinical picture of hereditary gastric cancer, suggesting RAD51D as a possible candidate gene for this condition, as previously proposed for RAD51C." (PMID 37239438, 2023).
bone marrow failure (3 papers, 2017 to 2025). "Notably, biallelic mutations in certain FA pathway genes, such as FANCS/BRCA1, FANCO/RAD51C, FANCR/RAD51, and FANCM can cause an FA-like disorder that shares the cancer predisposition of classical FA and, in some cases, the associated developmental abnormalities, but lacks bone marrow failure." (PMID 41155398, 2025).
colorectal tumor (3 papers, 2015 to 2024). "This indicates that Rad51C promoter methylation can regulate the expression of fusion gene Variants in colorectal tumors." (PMID 27296891, 2016). "Expression of Rad51C variants is associated with FANCD2 foci positive colorectal tumors and is associated with microsatellite stability in those tumors." (PMID 25669972, 2015). "Herein we report the identification of three Rad51C spliced transcript variants, in human colorectal tumors." (PMID 25669972, 2015). "Among 38 colorectal tumor RNA samples analyzed, 18 contained variant 1, 12 contained variant 2, 14 contained variant 3, and eight expressed full length Rad51C exclusively." (PMID 25669972, 2015). "This indicates that Rad51C promoter methylation can regulate the expression of variants in colorectal tumors." (PMID 25669972, 2015). "To evaluate the biological function of the variant 1, we performed In vitro transient overexpression of Rad51C variant 1 in HCT116 colorectal tumor cells." (PMID 25669972, 2015). "Here we report the expression of splice variants of Rad51C in colorectal tumors and cells and differences in the expression of these variants between malignant and normal phenotypes." (PMID 25669972, 2015). "We analyzed FANCD2 foci status and Rad51C variants expression in colorectal tumors." (PMID 25669972, 2015). "We have identified novel splice variants of Rad51C mRNA in colorectal tumors and cells." (PMID 25669972, 2015). "This is based upon the detection of basal pSer33-RPA32 levels, RAD51 foci, ATM, and RAD51C expression in formalin-fixed paraffin-embedded colorectal tumor samples or derived preclinical models." (PMID 39456536, 2024). "We identified two forms of fusion mRNAs between Rad51C and ATXN7 in the colorectal tumors, including a Variant 1 (fusion transcript between Rad51C exons 1–7 and ATXN7 exons 6–13), and a Variant 2 (between Rad51C exons 1–6 and ATXN7 exons 6–13)." (PMID 27296891, 2016). "Here we report expression of the novel fusion gene between Rad51C and ATXN7 in human colorectal tumors, as well as association of the fusion gene with functional impairment of the FA DNA repair pathway." (PMID 27296891, 2016). "In conclusion a chromosomal translocation between DNA repair gene Rad51C and Ataxin-7 has been identified in colorectal tumors." (PMID 27296891, 2016). "In conclusion we found a fusion gene between DNA repair gene Rad51C and neuro-cerebral ataxia Ataxin-7 gene in colorectal tumors." (PMID 27296891, 2016). "The sequence analysis of the bisulfite treated DNA from six colorectal tumors showed three sites that are methylated in the identical position in the promoter region of Rad51C." (PMID 25669972, 2015). "We analyzed the promoter methylation pattern of the Rad51C tumor suppressor gene in the colorectal tumor cells." (PMID 25669972, 2015). "To investigate the expression of Rad51C in tumors, we isolated total RNA from colorectal tumors." (PMID 25669972, 2015). "In the current study we evaluated the frequency and expression of the fusion gene formed between Rad51C and ATXN7 in colorectal tumors and cell lines." (PMID 27296891, 2016).
glioma (3 papers, 2010 to 2024). A benign or malignant brain and spinal cord tumor that arises from glial cells (astrocytes, oligodendrocytes, ependymal cells). "We observed associations of methylation of RAD51 in glioma, and of RAD51C and RAD50 in CLLE." (PMID 33676569, 2021). "While RAD51C methylation was frequent in stomach adenocarcinoma (6%) and low-grade glioma (2.5%), it was mostly detected at a low tumour level, suggestive of heterozygous methylation, and was associated with CpG island methylator phenotype." (PMID 39055334, 2024). "However, only the RAD51C gene was induced in cisplatin-treated glioma cells, probably due to the high level of drug cytotoxicity at the conditions tested." (PMID 21637621, 2010).
infiltrating ductal carcinoma (3 papers, 2011 to 2020). "She transmitted RAD51C c.571 + 4A > G to her daughter diagnosed with BC (invasive ductal carcinoma, clinical stage I, ER, PR, and Her2 positive) at age 42 (PID: III‐4)." (PMID 31782267, 2020). "RAD51C c.571 + 4A > G heterozygotes diagnosed with OC all exhibited HGSC, and heterozygotes diagnosed with BC primarily exhibited invasive ductal carcinoma." (PMID 31782267, 2020).
anemia (2 papers, 2015 to 2022). A reduction in the number of red blood cells, the amount of hemoglobin, and/or the volume of packed red blood cells. "Biallelic RAD51C deleterious variants are also implicated in Fanconi anemia (FANCO)." (PMID 35740625, 2022). "RAD51C, also known as Fanconi anemia complementation group O (FANCO), is part of the RAD51 gene family and is essential for homologous recombination repair." (PMID 26484312, 2015).
infertile (2 papers, 2018 to 2025). "One hint comes from mice with a hypomorphic Rad51c allele, a fraction of which are infertile due to a substantially reduced level of RAD51C expression." (PMID 30305635, 2018). "Reproductive phenotype was primarily observed in homozygous mutant mice except for Nf1, Rad51C, and Wt1, whereby heterozygous mutant males present the sub- or infertility." (PMID 40060932, 2025).
leukemia (2 papers, 2019 to 2020). A malignant (clonal) hematologic disorder, involving hematopoietic stem cells and characterized by the presence of primitive or atypical myeloid or lymphoid cells in the bone marrow and the blood. "The proband's mother (PID: II‐7) and other available maternal relatives are wild‐type; therefore, we concluded that the colon, leukemia and other cancers are not attributed to the RAD51C c.571 + 4A > G variant." (PMID 31782267, 2020).
osteosarcoma (2 papers, 2019 to 2024). A usually aggressive malignant bone-forming mesenchymal neoplasm, predominantly affecting adolescents and young adults. "Given that CHO cells deficient for RAD51C, RAD51D, XRCC2 or XRCC3, and human HCT116 cells deficient for XRCC3 are viable, we attempted to disrupt each classical RAD51 paralog individually in transformed human osteosarcoma U2OS and human embryonic kidney HEK293 cells." (PMID 31584931, 2019).
ovarian tumor (2 papers, 2015 to 2022). "Recent studies on the Rad51C gene have shown 14 germline sequence alterations among 1100 breast and ovarian tumor samples from patients." (PMID 25669972, 2015).
Serous carcinoma (2 papers, 2021 to 2022).
angiosarcoma (1 paper, 2023). A malignant tumor arising from the endothelial cells of the blood vessels. "EME1, FANCA, RAD51, TP53BP1, RAD51C, RPA1, and XRCC2 exhibited alterations in more than half the cases of the angiosarcoma cohort." (PMID 36779660, 2023).
chordoma (1 paper, 2024). Chordomas are rare malignant tumors arising from embryonic remnants of the notochord in axial skeleton. "A 12-year-old male with a clival de-differentiated chordoma presented with a RAD51C pathogenic defect (c.706-2A > G/splice site)." (PMID 38700789, 2024). "All patients except for the RAD51C and FH heterozygotes, were referred to the NIH without prior knowledge of their germline status and had been followed according to the chordoma screening protocol, as recommended in the published guidelines by the Chordoma Global Consensus Group in 2017." (PMID 38700789, 2024).
colon adenocarcinoma (1 paper, 2024). "These cases, as well as low-level meRAD51C colon adenocarcinoma (COAD) and HNSC, also mostly exhibited low HRD scores, absence of Signature 3 and absence of RAD51C LOH." (PMID 39055334, 2024).
endometrial tumor (1 paper, 2021). "Tumor mutational signatures provided evidence that germline variation in BRCA1, PALB2, RAD51C, MUTYH and NTHL1 can be (but is not always) associated with tumor mutational signatures consistent with a functional role of these genes in endometrial tumor development." (PMID 33917078, 2021).
germ cell tumor (1 paper, 2021). A benign or malignant, gonadal or extragonadal neoplasm that originates from germ cells. "We showed differential response of germ cell tumor cell lines to Olaparib, associated with BRCA1/RAD51C promoter methylation." (PMID 33513287, 2021).
glioblastoma (1 paper, 2022). The most malignant astrocytic tumor (WHO grade IV). "From the 84 DDR genes assessed, the high expression of ATP23, RAD51C and RPA3 was independently associated with poor OS outcomes in the TCGA IDH wild-type glioblastoma cohort." (PMID 35406779, 2022). "At the gene level, the high expression of ATP23, RAD51C and RPA3 independently associated with poor prognosis in glioblastoma patients." (PMID 35406779, 2022).
invasive carcinoma (1 paper, 2020). A carcinoma that is not confined to the epithelium, and has spread to the surrounding stroma. "Individuals with pathogenic RAD51C variants in BC were previously reported to be primarily ductal, hormone receptor‐positive and HER2‐negative, or triple negative invasive carcinomas of no special type, diagnosed at an early stage with moderate differentiation, and OC is primarily HGSC." (PMID 31782267, 2020).
invasive lobular carcinoma (1 paper, 2020). "Three of the proband's sisters are also RAD51C c.571 + 4A > G heterozygotes, including one diagnosed with BC (invasive lobular carcinoma, clinical stage II) diagnosed at age 48 (PID: II‐3)." (PMID 31782267, 2020).
lobular carcinoma (1 paper, 2020). "The woman carrying the RAD51C missense gene alteration had a bilateral metachronous BC, a lobular carcinoma on the left, and a high-grade triple-negative invasive DC occurred 11 years later on the right." (PMID 32957588, 2020).
lung squamous cell carcinoma (1 paper, 2024). "For lung squamous cell carcinoma, 11 genes were causally related, comprising COPA, NCSTN, U91328.19, GABBR1, IER3, HLA-DQB1-AS1, HLA-DQB2, ANKRD26, PKD2L1, PSMA4 and RAD51C." (PMID 38834983, 2024).
mucinous adenocarcinoma (1 paper, 2015). An invasive adenocarcinoma composed of malignant glandular cells which contain intracytoplasmic mucin. "A novel c.379_380insG (p.P127Rfs*28) variant in RAD51C was found in a young OC patient who died 12 months after a diagnosis of mucinous adenocarcinoma." (PMID 26057125, 2015).
Muir-Torre syndrome (1 paper, 2021). Muir-Torre syndrome (MTS) is a form of hereditary nonpolyposis colon cancer (HNPCC) characterized by cutaneous sebaceous tumors, keratoacanthomas and at least one visceral malignancy, most frequently gastrointestinal carcinoma.
myeloma (1 paper, 2021). "The acquired melphalan-resistant myeloma cell line was found to express FANCF and RAD51C, which are involved in the FA/BRCA pathway and ICL repair." (PMID 33525741, 2021). "Melphalan-resistant myeloma cell lines consistently express FANCF and RAD51C, which are involved in the FA/BRCA pathway for ICL repair, and depletion of FANCF overcomes melphalan resistance." (PMID 33525741, 2021).
ovarian endometrioid carcinoma (1 paper, 2025). "These included alterations in RAD51C, NOTCH4, SMARCA4, SMARCA1 and JAK1 in ovarian endometrioid carcinomas and SMARCA4 genes in ovarian mucinous carcinomas." (PMID 40981433, 2025).
ovarian mucinous carcinomas (1 paper, 2025). "In addition to identifying genes previously known to be involved in these tumors, we identified alterations in RAD51C, NOTCH4, SMARCA1/4, and JAK1 in ovarian endometrioid, ESR1 in uterine endometrioid, and SMARCA4 in ovarian mucinous carcinomas." (PMID 40981433, 2025).
prostate tumor (1 paper, 2018). "On the other hand, as no loss of MSH6 expression was observed in the prostate tumor, this MSH6 variant is unlikely to explain the PrCa predisposition in this family, which is most likely related to the RAD51C truncation mutation or the ATM missense mutation also found in this patient." (PMID 29659569, 2018).
sebaceous gland carcinomas (1 paper, 2021). A cancer that involves the sebaceous gland.
skin toxicity (1 paper, 2025). "Similarly, RAD51C, like XRCC2, is vital for HR, and polymorphisms that diminish its activity can reduce repair fidelity and heighten acute skin toxicity." (PMID 40507362, 2025).